ENSG00000199783
Synonyms: LOC124900481
Gene: Small nucleolar RNA gene on chromosome 22 (24,901,147 to 24,901,214, reverse strand). Ensembl gene ENSG00000199783.
Gene Ontology:
Biological process: RNA processing
Cellular component: nucleolus
Homologues: Paralogues in human: SNORD56 (82% identical), SNORD56B (79% identical).